ACLY (ATP citrate lyase)
Diseases named in the same sentence as ACLY in open-access papers (continued):
Sharing a sentence is not in itself a finding about the gene and the disease.
prostate carcinoma (continued). "Activated AKT (AKT serine/threonine kinase) phosphorylates ACLY, resulting in sustained histone acetylation under glucose deprivation conditions, and pAKT (Ser473) was positively correlated with histone acetylation levels in human glioma and prostate cancers." (PMID 34050894, 2022). "ACLY expression is elevated in human prostate cancer and correlates with AR expression." (PMID 27248322, 2016). "Here, we examined the expression of enzymes involved in de novo lipogenesis (ATP-citrate lyase: ACLY), glucose uptake (Glucose Transporter 1: GLUT1), and folate-glutamate metabolism (Prostate-Specific Membrane Antigen: PSMA) as potential biomarkers of risk for early prostate cancer progression." (PMID 38003213, 2023). "Moreover, in the realm of prostate cancer, nuclear PDC has been shown to induce acetylation at histone 3 lysine 9 (H3K9) in the promoter regions of lipid‐associated genes, such as ACLY and squalene epoxidase, thereby facilitating lipogenesis and cellular proliferation." (PMID 38034101, 2023). "Among the enzymes discussed, ACLY, ENO, FASN, FAK, and PK are found in EVs from both breast and prostate cancers and contribute to the progression and survival of both cancers." (PMID 40214422, 2025). "AMPK activation reduces the expression of FASN and ATP-citrate lyase (ACLY) and inhibits the activity of SREBP1, which suppresses tumor development in breast and prostate cancer." (PMID 35896782, 2022). "Similar to prostate cancer, HCC has been shown to overexpress types of lipogenic enzymes, including acetyl-CoA carboxylase (ACC), ATP citrate lyase (ACL), and fatty acid synthase (FASN)." (PMID 35742944, 2022). "The ACLY-AMPK-AR network can be exploited to sensitize CRPC cells to AR antagonism, suggesting novel therapeutic opportunities for prostate cancer." (PMID 27248322, 2016). "Recent studies have found that Cu B can exert anticancer effects by inducing apoptosis and cell cycle arrest in human prostate cancer PC3 cells through down-regulation of the JAK/STAT signaling pathway, as well as inhibiting prostate cancer growth by inactivating ATP-citrate lyase." (PMID 39273281, 2024). "ACLY cleaves citrate into oxaloacetate and acetyl-CoA, ACLY is essential for tumorigenesis in mouse cancer models, and its compound inhibitors with high IC50 values have antitumor efficacy in xenograft models of lung and prostate cancer." (PMID 37164974, 2023). "ACLY is necessary for tumorigenesis in mouse models of cancer, and the tool compound inhibitors of ACLY with high IC50 values have been reported to have anti-tumor efficacy in xenograft models of lung and prostate cancer." (PMID 37958642, 2023). "Indeed, recent reports show that the expression of both ACLY and ACSS2 is increased at protein levels in prostate cancer tissue." (PMID 36497382, 2022). "Cucurbitacin B is another natural ACLY inhibitor found in cucumber, which inhibits the proliferation of prostate cancer cells by inducing apoptosis and does not have a significant impact on normal prostate epithelial cells." (PMID 39086974, 2022). "Additionally, Lipid synthesis is increased in prostate cancer and Lipogenic enzyme, such as fatty acid synthase (FASN), ATP citrate lyase (ACLY) and acetyl-CoA carboxylase α (ACACA) is highly overexpressed in prostate cancer." (PMID 29163775, 2017). "We identify a feedback loop between ATP-citrate lyase (ACLY)-dependent fatty acid synthesis, AMPK, and the AR in prostate cancer cells that could contribute to therapeutic resistance by maintaining AR levels." (PMID 27248322, 2016). "Accordingly, a recent study unveiled a novel metabolic function of MYC in regulation of fatty acid synthesis in prostate cancer, indicate that inhibition of fatty acid synthesis by targeting MYC ACLY/ACC1/FASN axis may be a viable strategy for prevention and/or therapy of prostate cancer." (PMID 39538125, 2024).
prostate carcinoma (continued). "This has been reported in prostate cancer cells, which could be inhibited only by C75 and SB204990, inhibitors of FASN and ACLY, respectively, in the absence of lipoprotein, the transporter of exogenous fatty acid and cholesterol." (PMID 30180878, 2018).
COVID-19 (29 papers, 2020 to 2025). A disease caused by infection with severe acute respiratory syndrome coronavirus 2. "In addition to the potential inhibition of the Krebs cycle, ATP citrate lyase activity could also explain the altered levels of citrate in mild COVID-19 patients." (PMID 33737694, 2021).
Hepatic steatosis (28 papers, 2018 to 2025). Steatosis is a term used to denote lipid accumulation within hepatocytes. "Hepatic steatosis is intricately associated with the ubiquitination of ATP citrate lyase (ACLY), lipid droplet‐encapsulated protein, and Kindlin‐2‐related proteins." (PMID 39355507, 2024). "Our data showed that PFOS exposure caused hepatic steatosis, as evidenced by significant increases in triglyceride levels, expression of ATP-citrate lyase, and fatty acid synthase, as well as fasting insulin levels." (PMID 38075064, 2023). "ACLY links carbohydrate and lipid metabolism, with high expression linked to fatty liver and NAFLD." (PMID 40018642, 2025). "Liver-specific ACLY deficiency protects mice from hepatic steatosis and dyslipidemia." (PMID 32530819, 2020). "Several studies have demonstrated that targeting ACLY ameliorates hepatic steatosis and hyperglycemia, yet its role in hepatic gluconeogenesis has remained largely unexplored." (PMID 41220581, 2025). "Inhibition of ACLY has been shown to alleviate hepatic steatosis and improve glucose control in animal models of metabolic syndrome." (PMID 41220581, 2025). "In animal models, BemA, by inhibiting ACLY, has demonstrated efficacy in reducing hepatic steatosis and preventing the progression of MASLD to MASH by impairing the activation and proliferation of HSC, thereby reducing fibrosis." (PMID 39000046, 2024). "In mice, inhibition of ACLY reduces liver steatosis, ballooning, and fibrosis and inhibits activation of hepatic stellate cells." (PMID 37729871, 2023). "In vitro and in vivo studies have revealed that Ly6d regulates hepatic steatosis by means of phosphorylation of ATP citrate lyase (Acly)." (PMID 37394588, 2023). "Increasing studies have revealed the role of ACLY in tumors and cardiovascular and fatty liver diseases." (PMID 37414769, 2023). "Alterations in the expression or activation of ACLY have been observed in various metabolic and pathological conditions, such as cancer and fatty liver diseases." (PMID 37414769, 2023). "It is well illustrated that ACLY participates in promoting cancer metastasis and fatty liver diseases." (PMID 37414769, 2023). "Accordingly, SUA enhances lipogenesis by activating ATP-citrate lyase and inhibiting both mitochondrial aconitase activity and AMP-activated kinase (AMPK) phosphorylation, thus predisposing to hepatic steatosis." (PMID 35402521, 2022). "In fact, abnormal expression or activity of ACLY has been found in hepatic steatosis, dyslipidemia, diabetes and types of cancers, including colon cancer." (PMID 35177584, 2022). "In this study we investigated the regulation of ACLY expression in an in vitro model of hepatic steatosis, represented by HepG2 cells treated with a mixture of palmitic and oleic fatty acids." (PMID 32054087, 2020). "ATP citrate lyase is related to hepatic steatosis and dyslipidemia." (PMID 39861357, 2025). "Bempedoic acid (BA, ETC1002) is an ACLY inhibitor that has shown therapeutic potential for fatty liver disease by inhibiting the hepatic PXR-SLC13A5/ACLY signaling axis, and it may serve as a supplementary therapy for patients who are intolerant to statins." (PMID 40362316, 2025). "Thus, in leptin receptor-deficient mice, knocking down hepatic ACLY expression protected against hepatic steatosis, whereas hepatic ACLY abrogation increased TG levels in the liver in wild-type mice fed either a low-fat or a high-fat diet." (PMID 35884822, 2022). "In mice, it has been observed that dysregulation of ACLY is correlated to hepatic steatosis and IR." (PMID 32054087, 2020). "The role of ACLY in the development of hepatic steatosis has been poorly studied so far." (PMID 32054087, 2020). "Mice with a liver specific deletion of PTEN have increased levels of ACLY and ACSS2, and they develop fatty liver disease by early adulthood." (PMID 40636718, 2025).
Hepatic steatosis (continued). "Animal studies have revealed that elevated hepatic de novo lipogenesis contributes significantly to MASLD, and inhibition of ATP-citrate lyase (ACLY), a key enzyme in lipogenesis, has been shown to effectively control hepatic steatosis." (PMID 39000046, 2024). "Recent studies have shown that inhibiting SREBP1, ACLY, ACSS2, ACACA, and FASN can improve fatty liver disease." (PMID 37065701, 2023). "Furthermore, it can downregulate the expression of SREBP-1, acetyl-CoA carboxylase (ACC), ATP- citrate lyase (ACLY), and FAS, decrease the levels of TC and TG, and ameliorate liver steatosis." (PMID 36175900, 2022). "The result showed that HSD can significantly activate the de novo synthesis of endogenous fatty acids [fatty acid synthase (FASN), ATP citrate lyase (ACLY), and acetyl-CoA carboxylase (ACC)] in the liver, although hepatic steatosis was not severe." (PMID 35928832, 2022).
Obesity (26 papers, 2010 to 2026). Accumulation of substantial excess body fat. "Concurrent administration of drugs linked to obesity (estradiol, insulin, and leptin) promotes ACLY nuclear translocation through Akt-mediated phosphorylation of ACLY at Ser455." (PMID 36072980, 2022). "Collectively, these findings uncover a mechanism linking ACLY to copper homeostasis in BAT and highlight SST as a promising repurposed candidate for correcting obesity and BAT dysfunction-associated metabolic disorders." (PMID 42109886, 2026). "In obesity-related kidney injury, ACLY drives renal ectopic lipid accumulation and inflammation by providing substrates for adipogenic enzymes and inducing histone hyperacetylation." (PMID 41958067, 2026). "We aimed to evaluate the role of an ATP-citrate lyase inhibitor as a novel treatment for obesity-related nephropathy by attenuating ELA in the kidney and the ensuing inflammation." (PMID 36568100, 2022). "In this case, lipid synthesis-related enzymes such as ACC1, FASN, and ATP citrate lyase (ACL) are decreased, which in turn reduced diet-induced obesity." (PMID 35359351, 2022). "We evaluated a novel treatment for obesity-related renal, an ATP-citrate lyase (ACL) inhibitor, to attenuate ectopic lipid accumulation (ELA) in the kidney and the ensuing inflammation." (PMID 36568100, 2022). "ChREBP activation in WAT is altered in obesity, resulting in the downregulation of ChREBPβ, ACLY, ACACA, FASN, and ELOVL6." (PMID 32085416, 2020). "HCA has long been known for its anti-obesity activity by inhibiting ACLY, a key enzyme of fatty acid biosynthesis." (PMID 33096779, 2020). "ACLY play a crucial role in obesity-related complications in glucose and lipid homeostasis of mice liver." (PMID 28396714, 2017). "The observed effect is credited to the anti-obesity activity of HCA, which inhibits the activity of ACLY." (PMID 39835169, 2025). "The major mechanism of G. cambogia’s anti-obesity effect is the inhibition of ATP-citrate lyase (ACL) by HCA, which binds to ACL instead of citric acid, thus reducing the production of acetyl CoA." (PMID 37111078, 2023). "Third, obesity‐related factors, such as insulin and leptin, induce AKT‐mediated phosphorylation of ACLY at Ser455 to promote the nuclear translocation of ACLY, which increases histone acetylation levels and upregulates the pyrimidine metabolism gene DHODH and ultimately promotes tumors." (PMID 39584783, 2024). "Finding an appropriate animal model that mimics ACLY down-regulation observed in human HF has also been difficult, as our initial survey of pressure-overload, diet-induced obesity, and an HFpEF model (L-NAME + high fat diet) showed that none exhibit such behavior." (PMID 40499285, 2025). "Furthermore, links to fatty acid synthesis were discovered, that could be relevant for understanding insulin resistance and obesity, such as the dual action of BDK and PPM1K on both BCKDH complex and ACLY." (PMID 39198298, 2024). "The relative contributions of ACLY and ACSS2 to AcCoA production and DNL flux have not been studied in the context of the most common experimental model of obesity, its induction by feeding with HFD." (PMID 35988648, 2022).
ovarian carcinoma (22 papers, 2012 to 2025). A malignant neoplasm originating from the surface ovarian epithelium. "High ACLY expression was found in gastric adenocarcinoma patients, correlated with advanced stages and lymph node metastasis, ACLY also shows a strong association with poor prognosis in various cancers like ovarian cancer." (PMID 36172157, 2022). "Mechanismlly, by knockdown of ACLY expression could inhibit the proliferation of ovarian cancer A2780 cells and cause G1 phase arrest, suggesting that ACLY promoted cancer cell proliferation through the regulation of cell cycle." (PMID 33194756, 2020). "Pharmaceutical blockade of ACLY was reported to reverse the acquired cisplatin resistance in ovarian cancer." (PMID 40709184, 2025). "In ovarian cancer, the expression of ACLY is observed to have elevated compared to normal ovarian tissues, and increased expression level of phosphorylated ACLY in ovarian cancer was commonly associated with cancer grade, FIGO stage, and poorer prognosis." (PMID 40709184, 2025). "ACLY has been proposed as the key enzyme regulating acquired CDDP resistance in ovarian cancer and, therefore, as a suitable novel target for sensitization of ovarian tumours to platinum agents." (PMID 35887244, 2022). "USP13 gene is amplified in serious ovarian cancers and specifically deubiquitinates and thus upregulates two key metabolic key enzymes, ATP citrate lyase (ACLY) and oxoglutarate dehydrogenase (OGDH)." (PMID 35898882, 2022). "ATP citrate lyase (ACLY) has been shown to be a key metabolic enzyme and is associated with poor prognosis in various cancers, including ovarian cancer." (PMID 33816292, 2021). "Immunohistochemical analysis showed that the increased expression level of phosphorylated ACLY in ovarian cancer tissues was related to cancer grade, FIGO stage, and poor prognosis." (PMID 33194756, 2020). "As such, ACLY is upregulated in a variety of tumors, and inhibition of ACLY genetically or pharmacologically significantly inhibits tumor growth in lung, prostate, or ovarian cancer xenograft mice." (PMID 40814339, 2025). "Therefore, de novo FAs synthesis is upregulated in ovarian cancer, driven by increased ACLY, ACC, and FASN-mediated enzymatic activity, which promotes proliferation, metastasis, and chemoresistance." (PMID 40709184, 2025). "In our previous study, we identified that USP13 increased both energy production and biosynthesis in human ovarian cancer cells by stabilizing Oxoglutarate Dehydrogenase (OGDH) and ATP Citrate Lyase (ACLY), which are key metabolic enzymes driving the reprogramming of ovarian cancer cell metabolism." (PMID 35173307, 2022). "Several recent studies have reported that ATP citrate lyase, which uses citrate to synthesize acetyl CoA in a lipogenesis pathway for cell proliferation, is upregulated in some human cancers such as lung, colorectal, and ovarian cancers." (PMID 27440433, 2016). "Inhibition of ACLY suppresses the AKT signaling pathway which is important in ovarian cancer." (PMID 25644622, 2015). "As expected, cardamonin decreased the level of free fatty acids and the protein expression of SREBP1, FASN, ACC, and ACLY, indicating that cardamonin inhibited DNL in ovarian cancer cells." (PMID 40315213, 2025). "Moreover, TNPO1, ACLY, NME1, FLOT1, and KLC4 are proteins already known to be involved in epithelial ovarian cancer." (PMID 37775701, 2023). "Furthermore, USP13 can deubiquitinate and stabilise ACLY/OGDH and c-Myc in ovarian cancer and glioblastoma, respectively, thereby functioning as an oncogene." (PMID 33627786, 2021). "In mice with lung, prostate, or ovarian cancer xenografts, either the genetic or the pharmacological inhibition of SREBP and ACLY has been shown to significantly suppress tumor growth and induce cancer cell death, making SREBP and/or ACLY promising therapeutic targets." (PMID 35198567, 2021).
colorectal cancer (21 papers, 2015 to 2025). A primary or metastatic malignant neoplasm that affects the colon or rectum. "This study investigates the deacetylation of ACLY at K978 acts as a novel risk in colorectal cancer chemoresistance." (PMID 41038802, 2025). "Our current study aims to assess the effects of functional single nucleotide polymorphisms (SNPs) in ACLY gene on recurrence and survival of colorectal cancer (CRC) patients." (PMID 25890184, 2015). "Collectively, these findings suggest that ZDHHC6 enhances the accumulation of lipid molecules by upregulating the expression of ACC and ACLY in colorectal cancer." (PMID 39148124, 2024). "Increased expression of PPARγ stimulates the production of lipids and the development of tumors, together with the activation of ACLY in colorectal cancer (CRC)." (PMID 39148124, 2024). "Ectopic overexpression of ATP-citrate lyase and insulin-like growth factor 1 receptor rescues the decreased colorectal cancer metastasis induced by HOXA13 knockdown." (PMID 34722321, 2021). "The ACLY gene has been evaluated for the prognosis and survival of colorectal cancer in the Chinese population." (PMID 33053772, 2020). "Moreover, ACLY overexpression in colorectal cancer can induce irinotecan resistance, which was reversed by ACLY knockdown." (PMID 33393219, 2021). "Rs2304497 and rs9912300 in the ACLY gene showed significant associations with the risks of death (HR [95% CIs]; 0.47 [0.24–0.90] and 0.59 [0.37–0.92], respectively) and recurrence (0.46 [0.24–0.86] and 0.54 [0.35–0.83], respectively) in patients with stage III + IV colorectal cancer." (PMID 33053772, 2020). "circAURKA suppressed the degradation of CTNNB1 protein by facilitating the interaction of ACLY with CTNNB1 protein, accelerating the growth and metastasis of colorectal cancer." (PMID 39858034, 2025). "ACLY also plays a significant role in the AKT signaling pathway, promoting the survival of drug-resistant colorectal cancer cells." (PMID 36064336, 2022). "In colorectal cancer, HOXA13 overexpression mediated by insulin-like growth factor 1 promotes metastasis through upregulating downstream targets ATP-citrate lyase and insulin-like growth factor 1 receptor." (PMID 34722321, 2021). "ATP-citrate lyase (ACLY) and acetyl-CoA carboxylase (ACC), the enzymes that convert citrate to acetyl-CoA and subsequently to malonyl-CoA in the cytoplasm, are upregulated in a number of cancers such as lung, liver, ovarian, and colorectal cancer." (PMID 35008394, 2022). "Indeed, MICA expression on melanoma cell lines FM55m1, FM86, FM78, and SK-MEL-28, colorectal cancer cell lines HT29 and SW480, as well as HeLa and HaCaT cells were sensitive to ACLY inhibition by HC." (PMID 32849657, 2020).